CD276 (CD276 molecule)
Diseases named in the same sentence as CD276 in open-access papers (continued):
Sharing a sentence is not in itself a finding about the gene and the disease.
tumor (continued). "The expression levels of immune checkpoints, including BTLA, VTCN1, CD276, PDCD1, CD160, NRP2, and CD200, as well as the tumor-associated fibroblast marker FAP, were found to be higher in the high-risk group." (PMID 40364849, 2025). "B7-H3 (CD276) is an immune checkpoint ligand initially described as a T-cell costimulator but now recognized for its role in tumor progression, metastasis, and immune evasion." (PMID 41373591, 2025). "Nevertheless, in patients from the TCGA dataset with high CD276 mRNA, several oncogenic gene signatures were enriched, while tumor suppressors were deleted." (PMID 40175626, 2025). "The consequent reduction in ALKBH5-mediated m6A demethylation on CD276 mRNA increases CD276 expression, facilitating immune evasion by suppressing cytotoxic T-cell activity and promoting tumor progression." (PMID 41359051, 2025). "recently developed a CD276-directed antibody-drug conjugate (ADC) that exhibited anti-tumor activity in non-small cell lung cancer (NSCLC) models, primarily by delivering a cytotoxic MMAF payload." (PMID 40821788, 2025). "Acting as an immune checkpoint molecule, CD276 plays a crucial role in immune evasion and the tumor immune microenvironment." (PMID 40255404, 2025). "B7-H3 (CD276), a member of the suppressive B7 family checkpoint molecules, is widely expressed in various human cancers and plays a crucial role in tumor progression." (PMID 39806405, 2025). "Nonetheless, across solid tumour applications (HER2, GD2, PSMA, and CD276), feasibility and proof of concept have been established; however, tumour heterogeneity and the suppressive tumour microenvironment remain major barriers to efficacy." (PMID 41465327, 2025). "To target CD276 with immunotherapy in SCLC, we evaluated two different CAR-constructs, which differ in their mechanism of tumor targeting: dCAR-T, which directly target CD276; and AdCAR-T, which indirectly target CD276 via an AM." (PMID 40722088, 2025). "Of note, a heatmap based on GSEA showed several tumor-associated immune checkpoints, such as H2-Ab1, CD86, CD80, and CD276, CD274 (Pdl1), were downregulated upon Prmt3 deletion." (PMID 40050608, 2025). "As a first step, we analyzed CD276 mRNA expression using TGCA TARGET GTEx data sets from tumor and matched normal tissues to assess relative expression levels." (PMID 40821788, 2025). "CD276 is broadly expressed on tumor cells and with relatively limited expression in normal tissues, making it an ideal candidate for antibody-based therapy, particularly Fc-engineered antibodies designed to enhance NK cell-mediated tumor cytotoxicity." (PMID 40821788, 2025). "Integrated characterization of tumor and immune features, a four-gene prognostic signature comprising CD276, MS4A1, IGFBP1, and CD200 was established." (PMID 41488652, 2025). "CD276 (cluster of differentiation 276, B7-H3) is emerging as a promising immunotherapy target due to its expression across multiple tumor types." (PMID 40707958, 2025). "CD276 is frequently overexpressed in numerous solid tumors, notably in breast cancer and brain tumors, where it contributes to the tumor progression." (PMID 40547029, 2025). "B7 homolog 3 (B7-H3/CD276), a type I transmembrane glycoprotein, is overexpressed in tumor tissues (including SCLC) but shows limited distribution in normal tissues." (PMID 41200177, 2025). "One promising target for new immunotherapeutic approaches is CD276 (B7-H3), which is highly expressed in multiple tumor types." (PMID 40707958, 2025). "B7-H3 (CD276) has emerged as a promising immunotherapeutic target due to its selective expression on tumor cells and neovasculature, with minimal presence in healthy tissues." (PMID 40881578, 2025). "To further enhance tumor specificity, we developed CD276 mAb-Exo-AAV to target and deliver the cmLumiOpto gene under the control of a tumor-selective cfos promoter." (PMID 41462289, 2025).
tumor (continued). "Present studies are focusing on the emerging anti‐tumor strategy that targets CD276 through CAR‐T cells, but the clinical proof of this therapeutic method has not been completed yet." (PMID 41223031, 2025). "CD276 is involved in immune escape mechanisms, tumor growth, and metastasis, making it an attractive target for patients unresponsive to PD-1/PD- L1-directed therapies." (PMID 40821788, 2025). "In a study, concentrations of circulating tumour-derived EVs expressing B7H3/CD276, Mucin-1 (MUC1), and EpCAM in DTC compared to HCs, all three are epithelial tumour markers known to be overexpressed in TC." (PMID 41193833, 2025). "CD276, which is highly expressed on the surface of HNSCC cells, helps tumour stem cells evade immune surveillance; blocking CD276 significantly inhibits lymph node metastasis and enhances antitumour immunity." (PMID 40181975, 2025). "Emerging solutions, such as dual-target CAR-T cells that simultaneously recognize two tumor-associated antigens (e.g., HER2/MUC1 or B7-H3/CD276), aim to counter antigen escape, enhance specificity, and reduce off-tumor toxicity." (PMID 41348261, 2025). "CD276 is highly expressed on tumor cells and tumor vasculature in a variety of solid tumor entities, while it is expressed at a low levels on healthy tissue." (PMID 40722088, 2025). "All three datasets saw a statistically significant upregulation of ULBP1/2 and CD276 in tumor samples versus adjacent normal tissue." (PMID 40013140, 2025). "CD276 is a transmembrane immune checkpoint molecule expressed on various tumor and stromal cells, exerting context-dependent co-stimulatory or co-inhibitory effects." (PMID 40936932, 2025). "The choice of CD276 as a target is based on the fact that it is expressed on both tumor cells and tumor vasculature across various tumor types." (PMID 40707958, 2025). "In the AML cell line U937, CD276 knockdown decreased survival, proliferation, colony formation, and tumor-growth in a xenograft model." (PMID 40175626, 2025). "Its high expression was linked to multiple immune regulatory genes and immune checkpoint genes in the tumor microenvironment, with a notable positive correlation with CD276 in most cancers." (PMID 40936932, 2025). "CD276 has been involved in tumor immunity, and has been studied as a potential target for cancer immunotherapy." (PMID 40853910, 2025). "Our in vitro and in vivo experiments demonstrate the role of CD276 in inducing T cell apoptosis and diminishing chemokine secretion, thereby dampening immune response and facilitating tumor progression." (PMID 41419460, 2025). "Recent advancements include novel antibody–drug conjugate (ADC) designs targeting diverse antigens, such as HER2, HER3, and CD276, demonstrating potent anti-tumor activity and improved strategies for drug delivery." (PMID 41007788, 2025). "For example, TAMs with high CD276 expression mediate “silent clearance, ” which protects tumor cells, and the antibody blockade of CD276 synergizes with PD‐1 inhibitors." (PMID 41403915, 2025). "Comparing normal kidney to ccRCC we show that CD276 expression is upregulated in mouse and human tumours as shown by bulk RNA-seq as well as through proteomic analyses in human ccRCC." (PMID 40473819, 2025). "B7 homolog 3 (B7H3), also known as CD276, is highly overexpressed in tumor cells, related endothelial cells, cancer - associated fibroblasts (CAFs), macrophages, etc., but less so in normal tissues." (PMID 40808941, 2025). "Elevated expression of CD276 on tumors contributes to the suppression of anti-tumor T-cell responses and correlates with a poor prognosis." (PMID 38937712, 2024). "The results of the COX univariate analysis indicate that PNI, NLR, PLR, SII, WHO grade, tumor diameter, CD276 expression levels, T stage, and N stage were correlated with PFI (p < 0.05)." (PMID 39210603, 2024).
tumor (continued). "In this study, we used a series of databases to perform a pan-cancer analysis of CD276, including the expression level of CD276 in pan-cancer and its relationship with tumor progression, patient survival duration, and immune cell infiltration." (PMID 39766794, 2024). "Recently, the target antigen CD276 (also known as B7-H3) has received large interest due to its broad but rather tumor-restricted expression on cancer cells and neovasculature/microenvironment, including CRC." (PMID 38410109, 2024). "Recent studies have shown that CD276 acted as a T-cell inhibitor to promote the proliferation, invasion, and tumor progression of cancers." (PMID 39766794, 2024). "Blocking CD276 has shown promise for the treatment of various solid cancers as it is a protein prolific protein across tumor sites, affecting tumor cells, dendritic cells, and macrophages." (PMID 39319055, 2024). "To validate the efficacy of our proposed libraries, we executed antibody discovery against an anti-tumor drug target: CD276 (also denoted as B7-H3)." (PMID 38671802, 2024). "B7H3 (CD276) suppresses tumor associated T cell activation, while induces tumor cell invasion and drug resistance." (PMID 38730433, 2024). "CD276, HLA-A, and TNFRSF4 are immune checkpoint proteins that are associated with tumor immune evasion." (PMID 39771050, 2024). "Using the TIMER2.0, GEPIA2, and UALCAN web resources, we found that the expression level of CD276 in 24 tumor tissues was significantly higher than that in adjacent normal tissues." (PMID 39766794, 2024). "The results of in vivo anti-tumor evaluation concurrent with CAR-T expansion detection showed that CD276 Dash CAR-T demonstrated enhanced anti-tumor efficacy, improved expansion and persistence in vivo functional validation." (PMID 38978106, 2024). "CD276 (B7-H3) is overexpressed in several tumors on both tumor cells and tumor vessels, constituting a promising target for immunotherapy." (PMID 39367484, 2024). "Leveraging this expression pattern, they developed an anti-CD276 drug conjugate, effectively targeting both tumor cells and infiltrating blood vessels." (PMID 39664380, 2024). "Proving the principle, we show that simultaneous blockade of CD276 and PD-1 restrain tumor growth better than any of the components as a single intervention." (PMID 38561369, 2024). "Based on the results of COX multivariate analysis, we utilized the expression levels of CD276 and tumor diameter to construct a nomogram for predicting postoperative PFI in patients with ccRCC, which holds significant clinical application value." (PMID 39210603, 2024). "Our results showed CD276 protein expression was upregulated in BLCA samples compared to para-tumor tissue samples." (PMID 38561369, 2024). "Our previous studies also confirmed that CD276 is highly expressed in ccRCC tissues; however, its expression is relatively low in tissues surrounding the tumor." (PMID 39210603, 2024). "In summary, our study demonstrates that CD276 is highly expressed on BC tissue, and treatment with the CD276xCD3 bsAb CC-3 effectively induces T cell anti-tumor immunity against BC target cells." (PMID 39367484, 2024). "CD276 expression correlates with aggressive phenotypes such as vascular invasion, advanced tumor staging, and the metastatic potential of HCC cell lines." (PMID 39640777, 2024). "For example, CD276 is upregulated in most tumor tissues and belongs to a newly discovered immunoregulatory protein family." (PMID 38970121, 2024). "Using RNA-Seq data for human RMS tumors (n = 98) and cell lines (n = 33), we confirmed that FGFR4 and CD276 were highly expressed in RMS compared to 147 normal tissues with significant heterogeneity among tumor samples." (PMID 39043633, 2024). "Further, we found a limited number of CD8+, mainly PD1high T cells, infiltrating into ITM areas where they are surrounded by PD-L1, CD73, CD155, and CD276 expressing tumor cells." (PMID 38566984, 2024).
tumor (continued). "Results from IHC staining showed comparable levels of cell proliferation and an increase in apoptotic events in the invasive tumor cells of CD276 cKO compared to the control tumors." (PMID 38561369, 2024). "Blocking CD276 can effectively enhance T cell-mediated antitumor immunity, eliminate cancer stem cells, and prevent tumor growth and metastasis." (PMID 38688977, 2024). "Current research is exploring therapeutic strategies targeting CD276 and its pathways to enhance anti-tumor immune responses, potentially improving the efficacy of existing treatments or leading to new interventions for CRC patients." (PMID 38979413, 2024). "Our findings indicate that CD56 and/or CD16 positive NK cells were frequently observed in CD276-expressing xenograft tumor tissue and also in the liver." (PMID 38566988, 2024). "A better understanding of CD276 functions in the context of tumor microenvironment will undoubtedly define the applications of CD276 blocked in a more precision way." (PMID 38561369, 2024). "We detected lower apoptotic rates in the invasive tumor cells of CD276 cKI tumors compared to the control tumors." (PMID 38561369, 2024). "More importantly, we demonstrated the manufacturing feasibility, acceptable safety and superior anti-tumor efficacy of CD276 Dash CAR-T generated with reduced time." (PMID 38978106, 2024). "Encouragingly, CD276 Dash CAR-T showed superior tumor-control ability than conventional CAR-T when administered at medium doses (3E6 CAR-T cells) and low doses (1E6 CAR-T cells)." (PMID 38978106, 2024). "In detail, both the medium- and low-dose CD276 Dash CAR-T groups achieved complete tumor eradication at 21 days after administration and remained tumor-free." (PMID 38978106, 2024). "The result showed that the genes (including CD276, CD274, and PDCD1LG2) had functions on T-cell co-inhibition contributing to tumor cell evasion were enriched in high-risk groups and become important targets for blockade-based immunotherapy in cancer;." (PMID 38665430, 2024). "Both PD-1 and CD276 are members of the B7 family, making their effects on the tumor microenvironment similar." (PMID 39136031, 2024). "Pronounced expression of CD276 was observed in all analyzed tumor samples including triple negative BC." (PMID 39367484, 2024). "Statistical contrast of normal tissue and primary tumor for CD276 mRNA expression in our study showed a significant (p < 0.0001) 4.03-fold increase in mRNA expression relative to normal tissue." (PMID 38539537, 2024). "Another example is CD276, an immunostimulatory checkpoint gene that inhibits tumor antigen-specific immune responses." (PMID 38396241, 2024). "By delving deeper into the relationship between CD276 expression and postoperative tumor staging, we discovered an increasing trend in CD276 levels in relation to advancing tumor stages." (PMID 39319055, 2024). "T-cells expressing dual targeting FGFR4.28HTM.28z-CD276.8HTM.BBz BiCisCAR demonstrated the highest level of tumor killing, T-cell expansion, persistence, and lowest degree of exhaustion." (PMID 39043633, 2024). "We constructed a CAR targeting CD276 and demonstrated clear evidence of anti-tumor activity of CD276 CAR-T against many cancer cell lines in vitro." (PMID 38978106, 2024). "Profoundly, we found that depletion of either CD4+ or CD8+ T cells resulted in impaired of tumor suppressive effects of TAM CD276 cKO on BLCA." (PMID 38561369, 2024). "B7-H3 (CD276) is highly expressed in many tumor entities, whereas expression on healthy tissues is more limited." (PMID 38322253, 2024). "Statistically significant differences were found between the two groups in terms of PNI, NLR, PLR, SII, WHO grading, tumor diameter, surgical method, CD276 expression, T stage, and N stage (p < 0.05)." (PMID 39210603, 2024). "CD276, which is a member of the B7 family of immune checkpoint proteins and is highly expressed in tumor cells, has also been seen to be expressed in CSCs in mouse HNSCC." (PMID 39335624, 2024).
tumor (continued). "Previous studies have proven that CAFs and MDSCs are among the main factors in the formation of an immune-inhibiting TME, indicating that CD276 is involved in the inhibition of anti-tumor immune response." (PMID 39766794, 2024). "NLRP1 is also significantly associated with most immune‐stimulating genes except for CD276, HHLA2, NTSE, PVR, TNFSF18 and UNBP1 in the HNSC‐excluded tumours." (PMID 39318060, 2024). "Despite the differences in CD276 surface expression, CC-3 induced strong tumor cell killing in both BC cell lines used." (PMID 39367484, 2024). "Subsequently, we separated epithelial cells to examine the molecular events in tumor cells in CD276 cKO mice." (PMID 38561369, 2024). "The larger the tumor diameter and the higher the tumor CD276 expression level, the shorter is the PFI." (PMID 39210603, 2024). "CD276 protein is broadly expressed in tumor lesion, including tumor cells, dendritic cells and macrophages, which makes CD276 blockade will lead to comprehensive consequences." (PMID 38561369, 2024). "The CD276 transmembrane protein, also known as B7-H3, is an immune checkpoint molecule expressed on the surface of tumor, antigen presenting and natural killer cells." (PMID 39431018, 2024). "B7-H3 (CD276), an immune checkpoint molecule, is overexpressed in various types of cancer and their tumor vasculature, demonstrating significant associations with adverse clinical outcomes." (PMID 38952550, 2024). "In contrast, a number of studies have shown that CD276 inhibits anti-tumor immunity, including suppression of CD4+ and CD8+ T cell activation and proliferation, and reduction of IL-2 and IFNγ production." (PMID 38637557, 2024). "In the current study, our single cell sequencing data revealed that CD276 mainly expressed in tumor cells, endothelial cells and TAMs." (PMID 38561369, 2024). "Nevertheless, both the CD276.8HTM.BBz single CAR and FGFR4.28HTM.28z-CD276.8HTM.BBz BiCisCAR T-cells controlled tumor and significantly increased survival, with the BiCisCAR demonstrating a swifter tumor clearance." (PMID 39043633, 2024). "Antigens such as B7-H6, CD30, CD70, and CD276 (B7-H3) are highly expressed on tumor cells but are also found on normal cells, thereby increasing the risk of nontumor cell targeting." (PMID 38915099, 2024). "This study tested the anti-tumor efficacy of CD276.CAR-T cells in vivo using subcutaneous and orthotopic xenograft mouse models of ESCC." (PMID 39417449, 2024). "This pronounced discrepancy clearly indicates that CD276 is overexpressed in BLCA tissues compared with adjacent non-tumor tissues." (PMID 39319055, 2024). "When tested in vivo, T-cells expressing FGFR4.28HTM.28z-CD276.8HTM.BBz BiCisCAR exhibited faster tumor eradication, increased persistence, and reduced expression of exhaustion markers such as CD39, PD-1, and LAG-3." (PMID 39043633, 2024). "Because of its putative immunosuppressive role and its broad but relatively tumor-specific expression CD276 is an attractive target for antibody-based immunotherapy." (PMID 38637557, 2024). "The risk score strongly correlated with the expression of VEGFA, VEGFB, CD276 and C10orf54, and each immune checkpoint was differentially expressed between normal and tumour samples." (PMID 38613352, 2024). "The FGFR4.28HTM.28z-CD276.8HTM.BBz BiCisCAR T-cells demonstrated superior tumor-killing activity than those of FGFR4.28HTM.BBz-CD276.8HTM.BBz in vitro." (PMID 39043633, 2024). "To identify genes regulated by CD276 in BLCA tumor cells, we performed differential expression analysis on epithelial pseudo-bulk transcriptomes from CD276 wKO and control samples." (PMID 38561369, 2024). "Our results showed depletion of CD276 in tumor microenvironment resulted in significant reduction of WT MB49 tumor growth and tumor size, indicating that stromal CD276 is essential in BLCA development." (PMID 38561369, 2024).